SNORA2B (small nucleolar RNA, H/ACA box 2B)
Synonyms: ACA2b
Gene: Small nucleolar RNA gene on chromosome 12 (48,667,457 to 48,667,593, reverse strand). Ensembl gene ENSG00000207313.
Gene Ontology:
Biological process: RNA processing
Cellular component: nucleolus
Homologues: Orthologues: chimpanzee SNORA2B (100% identical), macaque SNORA2B (98% identical), pig SNORA2B (94% identical), rat Snora2b (93% identical), mouse Snora2b (93% identical), rabbit SNORA2B (91% identical), rat LOC120102638 (91% identical), mouse Gm22704 (88% identical). Paralogues in human: SNORA2C (74% identical), SNORA2A (74% identical).
Diseases named in the same sentence as SNORA2B in open-access papers:
SNORA2B is named in the same sentence as 2 diseases in open-access papers, as found by Europe PMC text mining. Sharing a sentence is not in itself a finding about the gene and the disease. The quoted sentences say what the papers report.
colon cancer (1 paper, 2025). "In conclusion, we have developed a gene expression score, based on ZNF697, CTSC, SNORA2B, and OXLD1, that effectively stratifies patients with stage II colon cancer into low and high‐risk groups, facilitating the identification of patients who may benefit from adjuvant chemotherapy." (PMID 40478186, 2025). "A dichotomized score, derived from the combined expression of four RNAs (ZNF697, SNORA2B, CTSC and OXLD1), effectively predicted TTR in stage II colon cancer patients." (PMID 40478186, 2025).
ovarian carcinoma (1 paper, 2019). A malignant neoplasm originating from the surface ovarian epithelium. "Low expression of SNORA2B and SNORD19 is related to poor prognosis of ovarian cancer patients, and high expression of SNORD116-4 and SNORD89 is associated with poor prognosis of ovarian cancer patients." (PMID 31395064, 2019). "SNORA2B, on the other hand, was correlated with only two mRNAs and not participated in mRNA splicing in ovarian cancer." (PMID 31395064, 2019).